SPP1 (secreted phosphoprotein 1)
Diseases named in the same sentence as SPP1 in open-access papers (continued):
Sharing a sentence is not in itself a finding about the gene and the disease.
fibrosis (33 papers, 2012 to 2025). the formation of excess fibrous connective tissue in an organ or tissue in a reparative or reactive process. "Finally, the disease gene-association analysis on the DEGs without the respiratory tract disease filter showed that six DEGs (namely, ACTG2, AGER, COL1A1, COL3A1, IGF1, and SPP1) were associated with fibrosis." (PMID 39944354, 2024). "We innovatively revealed and validated the molecular changes in ferroptosis and SPP1+ Mac during the LFH fibrosis process." (PMID 40001138, 2025). "These suggested that SPP1+ Mac gradually replaces IL1B+ Mac as the primary intercellular signals during LFH fibrosis, exerting a more pronounced regulating influence." (PMID 40001138, 2025). "In support of this, Spp1 (osteopontin) also promotes muscle fibrosis in mdx mice through a matrix metalloproteinase-mediated processing of TGF-β in stromal cells." (PMID 37418531, 2023). "This requirement has been noted in a variety of fibrosis models, including bleomycin-induced fibrosis, and Spp1–/– mice had reduced collagen deposition and disorganized collagen fibrils at sites of injury." (PMID 26955063, 2016). "In the context of IPF, SPP1’s upregulation may exacerbate pulmonary inflammation and fibrosis." (PMID 38566986, 2024). "Serum SPP1 levels are elevated in individuals with a history of asbestos exposure who have both fibrosis and pleural plaques, but not in those with plaques or fibrosis alone." (PMID 40559389, 2025). "Given the lack of an in vivo functional assessment of gal-3+/Spp1+ macrophages and FAP interactions, the present findings only provide a correlative association with fibrosis and require further study." (PMID 37418531, 2023).
asthma (31 papers, 2010 to 2025). "In humans, polymorphism in the OPN gene (SPP1) has been shown to be associated with asthma in a Puerto Rican population." (PMID 22031818, 2011). "To determine if microbiome protects asthma in OPN knockout mice, we transplanted fecal microbiome (FMT, from normal mice) to Spp1−/− mice for 2 weeks." (PMID 40401951, 2025). "In asthma, SPP1 levels are elevated in the serum, sputum, and bronchial tissue of patients, with studies linking these levels to disease severity and the timing of onset." (PMID 40559389, 2025). "SPP1 expression is increased in serum, sputum, and bronchial tissue in asthma, correlating with disease severity, late-onset asthma, and airway remodeling." (PMID 41293726, 2025). "In an inhaled ovalbumin (OVA) model of chronic allergen-induced asthma, SPP1 expression correlates with collagen content and peribronchial smooth muscle area." (PMID 40559389, 2025). "MiRNA-181b-5p, on the other hand, showing reduced expression in people with asthma, is characterized by targeting the SPP1 molecule, i.e., phosphoprotein 1, otherwise known as osteopontin." (PMID 36979742, 2023). "Anotherexample is the expression of osteopontin (Spp1), which recently has been proposed toenhance Th2 responses and is related to human asthma severity." (PMID 21625544, 2011). "Additionally, serum SPP1 levels are significantly higher in subjects with late-onset asthma compared to those with early-onset asthma." (PMID 40559389, 2025). "The underlying key genes in asthma pathogenesis and those regulated by treatment including Adipoq, HMOX1, SPP1, Cyp2e1, TNC, MB, MPO, Col9a1, Ckmt2, and Erbb4 were taken as examples to illustrate the positions and relationships with other points and midline in the figure." (PMID 33531915, 2021). "AAMΦs express MMP12 and SPP1 (osteopontin) which have been shown to be increased in asthma." (PMID 25437859, 2014). "The most influential nodes (Fn1, Igf1, Ccl2, C3, Timp1, Cxcl12, Ccl4, Ccr2, Spp1, C3ar1, Cat, Cyp2e1, Muc5ac, Muc5b) were selected for further validation in the OVA-induced asthma and post-asthmatic fibrosis murine model." (PMID 35625754, 2022). "According to RNA-seq and qRT-PCR results, we found the SPP1 expression increased in asthma and decreased after BSYQF treatment which suggested that SPP1 might play important effect on the mechanism of BSYQF's anti-remodeling." (PMID 33531915, 2021). "Therefore, SPP1 plays a dual role in enabling ECM remodeling and EMT processes in asthma and COPD." (PMID 41293726, 2025). "A significant decrease in the expression of the Th1 polarization factor IFN-γ and a significant increase in the expression of the Th2 polarization factors IL-4 and GATA-3 in Spp1−/−+OVA mice, which suggests a lack of OPN, increases the Th2-polarized environment in asthma." (PMID 40401951, 2025).
Cirrhosis (30 papers, 2012 to 2025). A chronic disorder of the liver in which liver tissue becomes scarred and is partially replaced by regenerative nodules and fibrotic tissue resulting in loss of liver function. "In liver tissues, OPN is encoded by SPP1 and correlates with the extent of liver regeneration, cirrhosis, and tumor growth." (PMID 35560794, 2022). "And there was high expression of SPP1 in cirrhosis, which proximately suggested that SPP1 was associated with malignant phenotype." (PMID 36686660, 2022). "In our results, SPP1 was highly expressed in HCC patients and was increased in NK and Myeloid cells, suggesting that it is closely associated with the level of inflammation, and chronic inflammation leads to the progression of cirrhosis and HCC." (PMID 38515461, 2024). "Meanwhile, intrahepatic lymphangiogenesis was decreased in ACLF patients than that in cirrhosis patients, and the state of LyECs in the ACLF group was apoptotic and dysfunctional because of SPP1 secreted by infiltrating monocyte/macrophages." (PMID 35629036, 2022). "qRT-PCR and IHC staining of SPP1 showed that SPP1 expression in ACLF liver was extremely high compared with that in HC and cirrhosis livers." (PMID 35629036, 2022). "In human cirrhotic tissue SPP1 was upregulated and strongly correlated with IMP2 expression (R2 = 0.42 p = 0.006 in cirrhosis)." (PMID 31555647, 2019). "Additionally, ligand–receptor pairs such as SPP1–ITGAV, VTN–ITGAV, and HLA-related interactions were more active in cirrhosis, suggesting their potential roles in macrophage polarization, immune evasion, and tumor cell adhesion or migration." (PMID 41153430, 2025). "Additionally, the scar-associated macrophages (SAMs) differentiated by markers such as TREM2, CD9, SPP1, TNFSF12, and LGALS3 and PDGFRA+ myofibroblasts had an increased proportion in patients with cirrhosis." (PMID 39889710, 2025).
Arthritis (28 papers, 2014 to 2025). Inflammation of a joint. "Additionally, we localized genes linked to arthritis severity and disease risk to effector cell populations, including tissue resident SPP1+ macrophages and fibrin-associated myeloid cells." (PMID 40601776, 2025). "Strikingly, we find genes associated with arthritis severity (progression to extended oligoarticular disease) and risk of JIA to be strongly enriched in SPP1+ macrophages." (PMID 40601776, 2025). "Spp1 secreted from SFs in a collagen-induced arthritis model is known to promote osteoclast formation via PI3K/AKT signaling." (PMID 39563425, 2024). "The secretion of SPP1 by fibroblast-like synoviocytes promotes osteoclast formation through the PI3K/AKT signaling pathway in collagen-induced arthritis." (PMID 38041172, 2023). "AHR, CAV1, CRP, CXCL2, IRF1, SPP1 and other targets play important roles in the pathogenesis of arthritis and can be used as key targets for the treatment of arthritis." (PMID 37637408, 2023). "In collagen induced arthritis, SPP1 secreted by FLSs promotes the formation of osteoclast through PI3K/AKT signals." (PMID 37637408, 2023). "Therefore, ADRB2, AHR, CRP, IRF1, PTGS1, SPP1 and other targets can be used as potential targets for CC in the treatment of arthritis, and it is of great significance to explore its role of CC in the treatment of arthritis." (PMID 37637408, 2023). "Reference mapping showed that the majority of ICI-arthritis myeloid cells mapped onto four RA myeloid clusters: IL1B + FCN1 + HBEGF+, STAT1+ CXCL10+, SPP1+, and MERTK+ HBEGF+ clusters." (PMID 40662950, 2025).
head and neck cancer (27 papers, 2005 to 2025). A primary or metastatic malignant neoplasm affecting the head and neck. "SPP1 is a key gene in head and neck cancer, and its expression is closely related to the infiltration of immune cells, especially M2 macrophages, in head and neck cancer." (PMID 39323640, 2024). "Our results reveal that SPP1 might affect these factors for regulating the ferroptosis and lysosome, which has been proven to have effects on head and neck carcinoma." (PMID 34977258, 2021). "The results showed that SPP1 was over-expressed in patients with head-neck cancer, and the top 3 genes co-expressing with SPP1 were Matrix Metallopeptidase 9 (MMP9), Actin Related Protein 2/3 Complex Subunit 1B (ARPC1B) and Amyloid Beta Precursor Protein (APP)." (PMID 31849319, 2019). "In some studies, by comparing three separate comprehensive gene expression omnibus (GEO) databases, researchers claimed that overlapping differentially expressed genes like SPP1, POSTN, and COL1A2 could be used as potential diagnostic indicators of head and neck carcinoma." (PMID 33134377, 2020). "Co-expression analyses indicated that SPP1 was co-expressed with MMP9, ARPC1B, and APP in head-neck cancer." (PMID 31849319, 2019).
Hepatic steatosis (27 papers, 2012 to 2025). Steatosis is a term used to denote lipid accumulation within hepatocytes. "LGALS3, SLC51B and SPP1 expression were in close association with the outcome of hepatic steatosis in both experimental approaches." (PMID 35046474, 2022). "Furthermore, SPP1-expressing hepatic lipid-associated macrophages were shown to derive from bone marrow, replacing Kupffer cells (KCs) in metabolic-associated fatty liver disease." (PMID 38832018, 2024). "Mechanistically, MCT4 alleviated hepatic steatosis by regulating a group of hub genes such as Arg2, Olr1, Cd74, Mmp8, Irf7, Spp1, and Apoe, which in turn impacted multiple pathways involved in lipid metabolism and inflammatory response, such as PPAR, HIF-1, TNF, IL-17, PI3K-AKT, Wnt, and JAK-STAT." (PMID 40330148, 2025). "Indeed, fine-mapping of MPC in metabolic fatty liver disease revealed that Spp1 serves as a bona fide marker of monocyte-derived macrophages replacing resident Kupffer Cells after injury." (PMID 36807143, 2023). "Furthermore, other studies have confirmed that knocking out the SPP1 gene can aggravate the progression of fatty liver disease." (PMID 35514751, 2022).
metastatic tumors (27 papers, 2006 to 2026). "We confirmed our results using a third dataset, including 22 primary PCa and 29 CRPC BM samples (GSE32269), where we observed that SPP1 is significantly upregulated in the metastatic disease." (PMID 40753365, 2025). "In the metastatic tumors, our study predominantly found a significant increase in macrophages expressing CCL2, MGP, SPP1, and MMP9, which have been previously associated with tumor cell invasion, metastasis, and immunoresistance." (PMID 40858590, 2025). "In metastatic tumors, our study identified a significant presence of macrophages expressing CCL2, MGP, SPP1, and MMP9, which are associated with various aspects of tumor metastasis and may play a crucial role in preparing the metastatic niche for malignant cell growth." (PMID 40858590, 2025). "In CAFs from metastatic tumors, a decrease in CCL2, MMP-2, TNC, OPN, and TGFβ levels and an increase in only TIMP1, PDPN, and SPP1 mRNA levels (without an effect on protein levels) was observed after calcitriol treatment." (PMID 38360633, 2024). "What’s more, we noticed that SPP1, also known as osteopontin (OPN), had been reported to be a promising tumor marker for detecting metastatic disease in many tumors." (PMID 37386390, 2023). "We found six genes such as SPP1, VEGFA, POSTN, RUNX2, CD44, and FOXO1 that were consistently overexpressed in patients with bone metastasis compared to non-metastatic tumors." (PMID 36424413, 2022). "Collectively, we found that there is a large number of infiltrated immunosuppressive myeloid cells in PTs and MTs, and the SPP1+ and WDR45B+ TAMs may potentiate progression of primary and metastatic tumors in the liver." (PMID 38414027, 2024). "At the same time, we noticed that the level of expression is an independent variable from the presence of metastatic disease at diagnosis; these two characteristics indicate that high expression of SPP1 is not necessary for tumor progression or metastatic disease in OS." (PMID 17022822, 2006).
type 2 diabetes (27 papers, 2010 to 2025). "Type 2 diabetes is associated with increased APOE, BAX, MMP1, NFKB1, PDGFB, SPP1, and TGFB2." (PMID 35153741, 2021). "The top-ranking pathways enriched in the shared genes include “ECM-receptor interaction” (FRAS1/SPP1, P value = 4.92e-03), “growth hormone synthesis, secretion and action” (ADCY5/SOCS3, P value = 8.84e-03) and “type II diabetes mellitus” (SOCS3, P value = 0.055)." (PMID 35606885, 2022).
breast tumor (26 papers, 2004 to 2025). "We analyzed tissue samples from 282 independent patients, comparing the SPP1 protein expression levels between the breast tumors and their corresponding normal breast tissues using immunohistochemistry (IHC)." (PMID 39727934, 2024). "For example, small interfering RNA against SPP1 by intratumoral injection significantly suppressed breast tumor growth and angiogenesis in a mouse model." (PMID 34676217, 2021). "Gene expression of SPP1 was analysed in 101 ER+ breast tumours and Ct-values were finally obtained from 100 tumours." (PMID 31996744, 2020). "They showed that the mRNA level of SPP1 increased in non-invasive, invasive and metastatic breast tumour tissue compared to normal breast tissue." (PMID 21314937, 2011). "SPP1 is an RGD-binding glycoprotein that plays a prominent role in important steps in breast tumor growth and metastasis." (PMID 18328103, 2008).
ischemic stroke (26 papers, 2014 to 2026). A stroke disorder caused by obstruction of blood flow to the brain, due to thrombotic (local blood clot formation) or embolic (due to a blood clot or other material traveling from another site) event. "Using qPCR, we successfully validated several key genes regarding CD11c-associated molecules (Itgax, Gpnmb, Gpx3, Csf1, Spp1, Igf1) in the sham group, Day 7, Day 14, and Day 30 after ischemic stroke." (PMID 36828819, 2023). "Previous studies on Spp1 have mainly focused on its role in brain development, ischemic stroke, and AD." (PMID 41549460, 2026). "Dissection of the NVU transcriptome revealed Spp1, encoding for osteopontin, to be highly upregulated in all NVU cells 24 h after ischemic stroke." (PMID 35752654, 2022). "Here we found that M15 (vitamin K in H. rhamnoides) is capable of inhibiting SPP1, thus elucidating the role of SPP1 in ischemic stroke pathophysiology." (PMID 26101539, 2015). "Spp1 has also been shown to exert a protective role in an ischemic stroke mouse model." (PMID 41549460, 2026). "Additionally, Spp1 expression is increased in ischemic stroke and exerts a neuroprotective effect." (PMID 38253182, 2024). "Considering that TNF, SPP1, MIF, and GALECTIN signaling pathways are involved in various forms of programed cell death (PCD), we hypothesized that PANoptosis contributes critically to ischemic stroke pathology." (PMID 41235394, 2025). "However, as these targets may be critically regulated by Spp1, which shows the strongest upregulation in all the major NVU cell types in our data set, we focused on evaluating the role of OPN in NVU and BBB function and its value as a therapeutic target in acute ischemic stroke treatment." (PMID 35752654, 2022).
head and neck squamous cell carcinoma (25 papers, 2008 to 2026). A squamous cell carcinoma that arises from any of the following anatomic sites: lip and oral cavity, nasal cavity, paranasal sinuses, pharynx, larynx, and salivary glands. "Recent studies have demonstrated that the expression of CXCL9 and SPP1 (CS) exhibits a strong prognostic association, surpassing traditional M1 and M2 markers, as revealed by single-cell analysis in head and neck squamous cell carcinoma." (PMID 40936719, 2025). "SPP1+monocytes display M2-like macrophage characteristics associated with reduced antitumor activity, promotion of tumor angiogenesis and enhanced tumor progression, which have been linked to immunosuppression and poor prognosis in other malignancies, such as head and neck squamous cell carcinoma." (PMID 41567210, 2025). "In head and neck squamous cell carcinoma (HNSCC), SPP1+CCL18+ and SPP1+FOLR2+ tumor-associated macrophages (TAMs) harbored pro-angiogenic and metastatic transcriptional programs and were correlated with poor survival." (PMID 39409192, 2024). "It has been illustrated that the expression of CXCL9 and SPP1 in macrophages at the single-cell level in head and neck squamous cell carcinoma is largely mutually exclusive, with CS polarity serving as a predictive factor." (PMID 40936719, 2025). "The results showed that the mRNA and protein expression of GSK3B, PIK3CA, FN1, MET, and SPP1 was significantly upregulated in head and neck squamous cell carcinoma tissues, while MAPK3 was significantly downregulated." (PMID 39323640, 2024). "SPP1 co-expression profiles were determined in 41 head-neck squamous cell carcinoma and 13 normal tissues." (PMID 31849319, 2019). "Moreover, the exclusive expression of CXCL9 and SPP1 in TAMs within ccRCC samples corroborates with the findings in head and neck squamous cell carcinoma." (PMID 38222314, 2024). "In head and neck squamous cell carcinoma (HNSCC), SPP1 overexpression is prognostic of worse survival results." (PMID 36303551, 2022). "In addition, SPP1 could promote proliferation and inhibit apoptosis in head and neck squamous cell carcinoma." (PMID 36038839, 2022). "Studies on head and neck squamous cell carcinoma have identified two pro-angiogenic and metastatic TAM subpopulations: SPP1 + CCL18 + and SPP1 + FOLR2 + clusters." (PMID 41391064, 2025). "For example, SPP1, encoding osteopontin, plays a crucial role in cell-matrix interactions and promotes tumor progression across various cancers, including CRC, prostate cancer, ovarian cancer, cervical cancer, and head and neck squamous cell carcinoma (HNSCC)." (PMID 39401197, 2024). "However, SPP1 in head and neck squamous cell carcinoma (HNSCC) remains unknown." (PMID 34977258, 2021). "Moreover, SPP1+ macrophages augment the secretion of TNF-α and IL-1β via the NF-κB pathway, further supporting proliferation in head and neck squamous cell carcinoma (HNSCC)." (PMID 41417432, 2025).